THYN1 (thymocyte nuclear protein 1)
Description:
Specifically binds 5-hydroxymethylcytosine (5hmC), suggesting that it acts as a specific reader of 5hmC.
Synonyms: THY28; HSPC144; MDS012; MY105; THY28KD
Tractability: PROTAC: ubiquitination databases record sites on it; its protein half-life has been measured.
Gene: Protein-coding gene on chromosome 11 (134,248,270 to 134,253,370, reverse strand). Ensembl gene ENSG00000151500.
Subcellular location: Nucleus
Subcellular location (Human Protein Atlas): Nucleoli fibrillar center; Nucleoplasm; Cytosol
Gene Ontology:
Molecular function: protein binding
Cellular component: fibrillar center; nucleoplasm; nucleus
Genetic constraint (gnomAD): Loss-of-function variants: 32 observed, 31.77 expected, observed/expected ratio (o/e) 1.01, 90% interval 0.76 to 1.35. The upper end of that interval is the gene's LOEUF score, 1.35, which puts it in group 5 of 6, group 1 being the genes least tolerant of losing a copy. Missense variants: 259 observed, 286.58 expected, observed/expected ratio (o/e) 0.9, 90% interval 0.82 to 1. Synonymous variants: 107 observed, 97.11 expected, observed/expected ratio (o/e) 1.1, 90% interval 0.94 to 1.29.
Homologues: Orthologues: chimpanzee THYN1 (99% identical), macaque THYN1 (92% identical), pig THYN1 (85% identical), mouse Thyn1 (82% identical), guinea pig THYN1 (82% identical), rabbit THYN1 (80% identical), dog THYN1 (78% identical), rat Thyn1 (76% identical), zebrafish thyn1 (62% identical).
Diseases named in the same sentence as THYN1 in open-access papers:
THYN1 is named in the same sentence as 3 diseases in open-access papers, as found by Europe PMC text mining. Sharing a sentence is not in itself a finding about the gene and the disease. The quoted sentences say what the papers report.
B-cell lymphoma (1 paper, 2017). "The role of THYN1 in BC is currently unknown, however, downregulation of THYN1 has been correlated with the induction of apoptosis in a specific B-cell lymphoma cell line." (PMID 28122328, 2017).
Immunodeficiency (1 paper, 2021). Failure of the immune system to protect the body adequately from infection, due to the absence or insufficiency of some component process or substance. "The deletion of the FLI-1, ETS1, JAM3 and THYN1 genes was considered to be directly associated with the immunodeficiency exhibited by the patient." (PMID 34440371, 2021). "The expression of the THYN1 gene in these immune cells leads us to propose its implication in the immunodeficiency of JBS patients, along with FLI-1, ETS1, NFRKB and JAM3." (PMID 34440371, 2021). "ETS1, NFRKB, JAM3 and THYN1 genes could also play a role in the presence of immunodeficiency." (PMID 34440371, 2021).
cancer (1 paper, 2017). A tumor composed of atypical neoplastic, often pleomorphic cells that invade other tissues. "The role of PLEKHH2, USP47 and THYN1 has not been extensively studied in cancer progression." (PMID 28122328, 2017).